RNU5A-2P (RNA, U5A small nuclear 2, pseudogene)
Gene: Small nuclear RNA gene on chromosome 4 (81,334,303 to 81,334,418, forward strand). Ensembl gene ENSG00000207065.
Homologues: Orthologues: chimpanzee U5 (99% identical), macaque U5 (95% identical). Paralogues in human: RNU5A-6P (73% identical), RNU5A-5P (72% identical), RNU5E-7P (72% identical), RNU5B-2P (71% identical), RNU5E-4P (71% identical), RNU5E-5P (71% identical), RNU5A-3P (70% identical), RNU5A-4P (70% identical), RNU5A-7P (68% identical), RNU5E-6P (68% identical), RNU5F-7P (68% identical), RNU5F-3P (67% identical), and 13 more.